OCLN (occludin)
Diseases named in the same sentence as OCLN in open-access papers (continued):
Sharing a sentence is not in itself a finding about the gene and the disease.
Stroke (continued). "The recognition of occludin's pivotal role not only expands our understanding of the molecular mechanisms underpinning stroke pathogenesis but also introduces a potential avenue for clinical applications in the realm of stroke diagnostics." (PMID 39119484, 2024). "Additionally, esteemed neuroscience journals such as the Journal of Cerebral Blood, Stroke, and Aging and Disease have disseminated numerous high-quality research findings, emphasizing the pivotal role of occludin in BBB damage during ischemic stroke." (PMID 39119484, 2024). "Topics such as “blood–brain barrier” (13%), “occludin” (13%), and “ischemic stroke” (12%) also appear quite frequently, demonstrating a continued interest in understanding the role of proteins in the pathogenesis of strokes." (PMID 39119484, 2024). "Although ChR2-photoactivated glial cells can increase glutamate and neuronal excitotoxicity after ischemic brain damage, our results support the notion that ChR2-photostimulated astrocytes increase tight junction protein ZO-1, Occludin expression and decrease IgG exudation in PT stroke rats." (PMID 37196130, 2023). "We considered two possibilities: one is that occludin deficiency directly decreases claudin-5 and ZO-1, and the other is that occludin deficiency exacerbates tissue damage, including BBB destruction, after stroke, which secondarily leads to more severely reduced claudin-5 and ZO-1." (PMID 36806348, 2023). "Measurement of CBF immediately before and after stroke, and at 1 and 3 days after stroke, showed that the decrease in CBF throughout the infarcted hemisphere (excluding infarct lesions) was similar between the wild-type mice and the occludin-deficient mice." (PMID 36806348, 2023). "In conclusion, occludin deficiency increases BBB permeability, exacerbates tissue damage, and decreases angiogenesis after cerebral infarction, leading to the long-term worsening of functional recovery following stroke in mice." (PMID 36806348, 2023). "Thus, analysis of the spatiotemporal dynamics of occludin expression showed that it decreased, as did claudin-5 and ZO-1, in brain endothelial cells from ischemic lesions after stroke in wild-type mice." (PMID 36806348, 2023). "We also found that Ripk2 knockout mice had greater preservation of tight junction proteins Zona occludens-1 (ZO-1) and Occludin in the ipsilateral cortex 24 h after stroke, which was concurrent with lower levels of active-MMP-9, a major contributor to BBB opening." (PMID 37777791, 2023). "Interestingly, plasma occludin has gained attention in the context of blood-brain barrier damage, demonstrating fluctuating levels of occludin in different types of stroke." (PMID 37745643, 2023). "In our study, quantitative real-time PCR analyses revealed that, in wild-type mice, the mRNA level of occludin, as well as those of claudin-5 and ZO-1, decreased starting from the acute phase at 3 h after stroke, and the decline continued into the chronic phase 48 days after stroke." (PMID 36806348, 2023). "Given that occludin is reportedly involved in cell proliferation and apoptosis, we examined its effect on angiogenesis by analyzing Ki-67 expression in brain endothelial cells after stroke." (PMID 36806348, 2023). "Additionally, collapse of occludin oligomeric assemblies and movement of occludin away from the tight junction were observed in cerebral microvessels in rats subjected to hypoxia/reoxygenation stress, a component of stroke pathogenesis." (PMID 35163820, 2022). "Specific intervention, such as normobaric hyperoxia, could reduce the blood occludin level after stroke." (PMID 36032782, 2022). "Similarly, ZO-1 and occludin expression in the ischemic cortex was significantly decreased in a photothrombotic stroke model; however, their expression was unchanged in the contralateral hemisphere." (PMID 36085043, 2022). "The serum occludin level may be able to reflect the extent of BBB injury that affects the long-term prognosis for stroke patients." (PMID 33269096, 2020).
Stroke (continued). "Our previous study suggested that normobaric oxygen could protect the BBB, reducing the level of serum occludin after a stroke and improving the patient's 7-day NIHSS score." (PMID 33269096, 2020). "Finally, we combined with NIHSS score to explore the correlation between serum occludin and the 90-day prognosis of stroke." (PMID 33269096, 2020). "Further prospective cohort studies may be needed to analyze the serum occludin levels at different times and between different stroke subgroups." (PMID 33269096, 2020). "Furthermore, our data demonstrated that TGR5 or BRCA1 knockdown significantly reverses the neuro-protection of INT777 on stroke outcomes, as well as decreasing ZO-1 and occludin expression." (PMID 32381096, 2020). "Our data show that blood occludin levels correlates well with the extent of BBB damage at the early stroke stage, suggesting that pretreatment blood occludin levels may serve as a reliable biomarker to identify acute stroke patients at high risk of ICH." (PMID 28079139, 2017). "To examine whether the enhanced MMP9 activity in the peri-infarct region might affect the integrity of BBB, we measured the expression of tight-junction protein occludin in this region using immunofluorescence staining at 14 days after stroke." (PMID 26391329, 2015). "Through a systematic examination of occludin-related research, we aspire to identify knowledge gaps, highlight key findings, and pave the way for future investigations aimed at advancing our understanding of stroke pathology and refining therapeutic strategies." (PMID 39119484, 2024). "This bibliometric analysis explores the expansive landscape of occludin research, a key tight junction protein, during the years 2000–2023, shedding light on the global scientific contributions, collaborations, and emerging trends in this critical area of stroke pathogenesis." (PMID 39119484, 2024). "In another photochemically‐induced stroke mouse model, when the researchers assessed the intestinal barrier function, it was found that the intestinal permeability of mice increased 1 day after stroke, and ZO‐1, occludin, and claudin‐1 contents in the TJ were significantly decreased." (PMID 37309254, 2023). "The excessive accumulated inflammatory and oxidative mediators following stroke cause endothelial dysfunction, which leads to BBB breakdown, indicated by increased BBB permeability and the degradation of BBB structural components, including the endothelial tight junction proteins ZO-1 and occludin." (PMID 35761277, 2022). "Preventing occludin phosphorylation either genetically using vascular endothelial specific expression of the stable, S490A non-phosphorylatable form of occludin, or by inhibiting PKCbeta, blocked stroke-induced permeability while decreasing stroke volume and improving functional outcome." (PMID 36320068, 2022). "Moreover, rhEPO increases cerebral protein levels of the TJ protein OCLN in neonatal rodent stroke, ventilation-induced cerebral white matter injury in preterm lambs, and traumatic brain injury, indicating its protective potential against hypoxia-induced BBB disruption." (PMID 35955834, 2022). "Therefore, the present study aims to determine whether serum occludin level combined with NIHSS score can improve the predictive value of HT in stroke patients with reperfusion therapy, utilizing our previous study database." (PMID 34475814, 2021). "However, it is still unclear what the specific relationship between serum occludin, HT and long-term prognosis is, and whether there is any difference in serum occludin level between stroke and stroke mimic patients." (PMID 33269096, 2020). "In addition, this study shows that serum occludin concentrations in elderly stroke patients were higher than for other age groups, confirming that old age may be a risk factor for BBB injury." (PMID 33269096, 2020).
Stroke (continued). "In several models of neurological diseases, especially stroke or cerebral ischemia-reperfusion injury and Alzheimer's disease a link was established between decreased expression, disrupted organization or redistribution of claudin-5 and occludin and increased BBB permeability." (PMID 26834555, 2015). "When comparing the relationship between the IS group and SM group and the severity of a stroke, we found that IS patients had significantly higher serum GFAP, NFL, OCLN, Claudin-5, and ZO-1 levels in both groups as compared to SMs." (PMID 39595521, 2024). "In our study, we demonstrated that tight junction protein occludin degradation and BBB disruption were progressively worse with the potentially augmenting inflammation response in perioperative stroke mice." (PMID 35799259, 2022). "We further studied such complexes using markers for tight-junction proteins (occludin and claudin-5) and proteases (MMP2 and MMP9) that increase the permeability of the BBB during stroke." (PMID 32221863, 2021). "Using logistic regression, we developed a combined model with two prediction variables, the baseline serum occludin level and the NIHSS score, to predict the probability of HT event in the stroke patients with reperfusion therapy." (PMID 34475814, 2021). "Serum occludin level is related with blood brain barrier disruption, and the National Institute of Health stroke scale (NIHSS) score reflects stroke severity." (PMID 34475814, 2021). "The expression of tight junction (TJ) proteins (zonula occludens-1 (ZO-1), occludin, and claudin-1) was downregulated, and transmission electron microscopy (TEM) showed broken TJ of the intestinal mucosa after stroke." (PMID 33642941, 2021). "During a stroke, the BBB gets damaged, which is accompanied by changes in the concentrations and distributions of claudin-5, occludin, ZO-1, and other building blocks of the BBB." (PMID 33182224, 2020). "In the ipsilateral cerebral cortex of COX-2+/+ mice, levels of ZO-1, occludin, JAM-A, and collagen IV were markedly decreased after stroke." (PMID 32973660, 2020). "As such, this present study was designed to assess the effects of STVNA in our in vitro stroke model of the BBB.The integrity and permeability of the BBB are governed and maintained by tight junction proteins (TJPs) such as claudin-5 and occludin." (PMID 33192319, 2020). "MMP-9 upregulation results in the degradation of tight junction proteins such as ZO-1, occludin, and the basal lamina, ultimately triggering BBB disruption and brain edema in the acute stage of stroke." (PMID 33510620, 2020). "Co-stainings with Occludin, Von-Willebrand Factor and CD34 demonstrated localization of SVCT2 in brain capillary endothelial cells in the ischemic area after stroke." (PMID 21347255, 2011). "After stroke, SVCT2 was localized specifically in brain capillary endothelial cells immunoreactive for the tight junction marker Occludin and the endothelial cell markers VWF and CD34." (PMID 21347255, 2011). "In stroke, vascular endothelial cell (EC) dysfunction at the compromised BBB involves paracellular leakage, as evidenced by the degradation of tight junction (TJ) proteins including claudin-5 (CLDN5), occludin (OCLN), and zonula occludens-1 (ZO-1/TJP1)." (PMID 40866935, 2025). "Stroke increased calpain and VEGF genes while decreased occludin gene expression (p<0.001)." (PMID 40259962, 2024). "believed that Cldn3 and occludin could not only protect tight junctions and kept the BBB intact in stroke, but also promoted edema and infarction, as they described the ambivalent effects of sealing proteins." (PMID 35338575, 2022). "In the future, serum occludin combined with NIHSS score may better predict the disease severity and functional outcome of stroke patients after EVT." (PMID 35338575, 2022).
Stroke (continued). "In addition, salidroside reversed the decrease in tight junction proteins (such as claudin-5 and occludin) by inhibiting the activation of MMP-9 (a member of MMPs), which proved the improvement of BBB damage in experimental stroke rat models." (PMID 35462916, 2022). "Herein, we aimed to identify the incidence of END in stroke patients with successful EVT and whether postoperative serum occludin levels were correlated with the occurrence of END." (PMID 35338575, 2022). "Further pilot clinical study showed that although blood occludin significantly elevated in AIS compared with pseudo-stroke patients, blood occludin alone is not sufficient enough for HT prediction (AUC 0.73–0.77)." (PMID 34512266, 2021). "PARP suppression has been shown to diminish edema, preserve the tight junction protein, occludin, and decrease expression of the adhesion molecule, ICAM-1, in animal models of stroke, traumatic brain injury, meningitis, and MS, reducing leukocyte infiltration and brain inflammation." (PMID 27677851, 2016). "Therefore, the combination of serum occludin levels (representing the extent of BBB disruption) and NIHSS score (reflecting stroke severity) markedly increased the predictive value for HT, providing a new method for predicting HT in stroke patients with reperfusion therapy." (PMID 34475814, 2021).
ischemic stroke (58 papers, 2011 to 2025). A stroke disorder caused by obstruction of blood flow to the brain, due to thrombotic (local blood clot formation) or embolic (due to a blood clot or other material traveling from another site) event. "In a model of ischemic stroke using occluding deficient mice, we explored the functional role of occludin in cerebrovascular health during HIV infection." (PMID 40313365, 2025). "A study in 2017 using a rat model of ischemic stroke found that the occludin protein in TJs of brain microvessels caused by cerebral ischemia rapidly degraded." (PMID 37840921, 2023). "Decreased neurological function in occludin-deficient mice after ischemic stroke continued until the chronic phase." (PMID 36806348, 2023). "Wang's study showed that MiR‐30a inhibitor restored the loss of occludin in microvessels of ischemic stroke rats and attenuate BBB breakdown and ischemic infarction, which conduced better outcome." (PMID 35338575, 2022). "Our results show that the inhibition of NADPH oxidase by apocynin can significantly reduce the BBB damage caused by 2 h ischemic stroke accompanied by reducing the degradation of tight junction protein occludin." (PMID 34434231, 2021). "Our results showed that QKL protected the TJs including ZO-1, claudin-5, VE-Cadherin, and occludin from damage caused by ischemic stroke." (PMID 32908557, 2020). "Similar evidence of occludin fragmentation in the brain were already demonstrated in early ischemic stroke or bacterial meningitis, and associated to matrix metalloproteinase (MMP) activity." (PMID 32867861, 2020). "Increased levels of the 65-kDa band of occludin have been detected in models of ischemic stroke and are associated with BBB disruption." (PMID 29527151, 2018). "Our previous animal study reported that blood occludin level was well-correlated with the extent of BBB damage after ischemic stroke, and thus serum occludin may serve as a relevant biomarker for assessing the risk of HT before reperfusion therapy." (PMID 34475814, 2021). "And in BBB damage after ischemic stroke, ZO-1 and Claudin-5 were both documented to be degraded via autophagy-lysosome 21, 22, which were in accord with our finding to find ZO-1 and Occludin were damaged via autophagy-lysosome pathway after ischemic stroke." (PMID 39781452, 2025). "By employing different phase autophagy regulators and Cav-1 siRNA and pcDNA3.1 plasmid, we verified that the therapeutic efficacy of BMSC-sEVs on BBB integrity was Caveolin-1-dependent autophagic degradation of ZO-1 and Occludin after ischemic stroke." (PMID 39781452, 2025). "Fasudil, a Rho kinase inhibitor, is studied to prevent stress fiber formation and preserve the distribution of TJ proteins such as claudin-5 and occludin following ischemic stroke." (PMID 41361096, 2025). "Some studies have shown that serum levels of matrix metalloproteinase‐9 (MMP‐9), cellular fibronectin, and occludin can predict s‐HT in patients with ischemic stroke." (PMID 40135640, 2025). "It elucidates the impact of these conditions on the expression of tight junction proteins, notably occludin, within the brain's microvasculature during ischemic stroke." (PMID 39119484, 2024). "According to Bradford's law, these specialized journals collectively account for a significant portion of the total number of published articles on occludin in ischemic stroke." (PMID 39119484, 2024). "Twelve hours after ischemic stroke induction, brain right hemisphere tissues were collected and calpain I, calpainII, occludin and VEGF genes expression were quantified by Real-Time -PCR." (PMID 40259962, 2024). "Based on the outcomes derived from the cluster analysis of keywords, the subsequent recommendations are proposed for future investigations concerning the role of occludin in BBB damage during ischemic stroke." (PMID 39119484, 2024).